RELN (reelin)
Diseases named in the same sentence as RELN in open-access papers (continued):
Sharing a sentence is not in itself a finding about the gene and the disease.
Pachygyria (4 papers, 2016 to 2025). Pachygyria is a malformation of cortical development with abnormally wide gyri with sulci 1,5-3 cm apart and abnormally thick cortex measuring more than 5 mm (radiological definition). "Recently, it was reported that point mutations in human pachygyria patients (Reelin Y1821H, G1280E, and R913C) showed stronger activity than wild-type Reelin when overexpressed in embryonic mouse brains." (PMID 39931643, 2025). "Pachygyria-associated de novo heterozygous RELN variants behave as dominant-negative forms in vitro." (PMID 38980724, 2024). "Pachygyria-associated de novo monoallelic RELN variants behave as dominant-negative in vivo in both animal models and patients." (PMID 38980724, 2024). "The pachygyria-associated de novo heterozygous RELN variants acted as dominant-negative by preventing WT RELN secretion in culture, animal models, and patients, thereby causing dominant NMDs." (PMID 38980724, 2024). "Our functional studies demonstrated that all RELN variants associated with pachygyria (I650S/D556V, C539R, and R3207C) homogeneously behaved as LOF in the neuronal aggregation assay owing to the severe impairment of their secretion." (PMID 38980724, 2024). "This is attributable to the dominant-negative effect of heterozygous RELN variants here observed that will reduce secreted RELN levels to 20% in individuals with pachygyria (DN*, DN1, and DN2)." (PMID 38980724, 2024). "Here, we report 6 patients with heterozygous missense RELN variants, which expand the phenotypic spectrum of RELN-related cortical malformations to include pachygyria and polymicrogyria." (PMID 38980724, 2024). "This indicates that RELN assembles into large protein complexes also intracellularly, suggesting a possible mechanism through which the pachygyria-associated variants I650S/D556V, C539R, and R3207C retained the WT protein intracellularly and hindered its secretion." (PMID 38980724, 2024). "Hence, all evidence supporting the pathogenicity of RELN variants identified in the pachygyria patients reflects deficient levels of functional RELN in their developing neocortex that potentially disrupt RELN-dependent neuronal migration from its early steps." (PMID 38980724, 2024). "Using complementary in vitro and in vivo assessments, we demonstrated that all heterozygous RELN missense variants linked to pachygyria severely prevented its secretion and neuronal aggregation activity, serving as causal to the disorder through a dominant-negative mechanism." (PMID 38980724, 2024). "Recently, it was reported that some Reelin mutants found in patients with pachygyria inhibited the secretion of co-expressed wild-type (normal) Reelin in a dominant-negative fashion in transfected cultured cells." (PMID 39931643, 2025). "We correlate phenotypes of the described polymicrogyria and pachygyria patients with specific functional alterations of the RELN protein." (PMID 38980724, 2024). "Taken together, these observations indicate that the de novo variants in the patients with pachygyria and the inherited variants in patients MI1/2 and DN* cause, respectively, strong and mild deficiency in RELN secretion." (PMID 38980724, 2024). "Conversely, I650S and D556V variants identified in pachygyria patient DN* drove the formation of cell structures in which the GFP+ cells were spread throughout with their processes clearly misoriented, and, although expressing RELN, the mutant protein failed to accumulate in a central region." (PMID 38980724, 2024).
Parkinson disease (4 papers, 2020 to 2025). A progressive degenerative disorder of the central nervous system characterized by loss of dopamine producing neurons in the substantia nigra and the presence of Lewy bodies in the substantia nigra and locus coeruleus. "Reelin has been implicated in APP/Aβ protein processing and regulation of TAU phosphorylation, as observed in AD and Parkinson’s disease." (PMID 40867631, 2025).
tauopathy (4 papers, 2020 to 2025). Neurodegenerative disorders involving deposition of abnormal tau protein isoforms (tau proteins) in neurons and glial cells in the brain. "Further studies are needed to investigate the gain of function of this new variant and its relation to amyloidosis and tauopathy, as understanding this variant may give insight into how to increase Reelin signaling for therapeutic interventions." (PMID 37891846, 2023). "Recent studies also showed that the overexpression of Reelin in a mouse model of tauopathy (TgRln/VLW mice) led to a reduction in tau phosphorylation independently of the total tau, together with an improvement in LTP and cognition." (PMID 37891846, 2023). "Tauopathy was more extensive in the case with RELN-COLBOS compared to the APOECh homozygote, except for the ERC, which was largely spared in both, suggesting resilience in the case with RELN-COLBOS." (PMID 37188781, 2023). "The Reelin conditional KO in the tauopathy mouse model PS19 led to the exacerbation of age-related spatial cognitive impairments." (PMID 37891846, 2023). "We also observed that the abnormal limb-clasping response, which is a common consequence of tauopathy in mice, was significantly rescued in RELN-COLBOS mice with the Tau transgene." (PMID 37188781, 2023). "Although additional studies of this model are necessary, our findings strongly support our hypothesis that RELN-COLBOS is a GOF mutation and it is probably genetically implicated in the resilience to tauopathy." (PMID 37188781, 2023). "To attempt to correlate the phenotypes of RELN-COLBOS in mice and humans, we used a crossbreeding strategy, using our knockin mouse model and a tauopathy mouse model, specifically the STOCK Tg(Prnp-MAPT*P301L)JNPL3Hlmc mouse from the Hutton’s laboratory, distributed by Taconic Biosciences." (PMID 37188781, 2023). "In addition, the phosphorylation-dependent binding and subsequent degradation of Reelin-modified ApoE isoforms by LRP8 affects the interaction dynamic, and notably, ApoE4 competes with Reelin for this receptor, limiting Reelin signals, leading to increased tauopathy and amyloidogenesis." (PMID 40806482, 2025).
brain tumors (3 papers, 2021 to 2025). "In this work, we looked at the potential role of the glycoprotein reelin in the context of brain tumor therapy." (PMID 38543187, 2024). "While these findings are indicative of a potential role for reelin in brain tumor biology, they lack clinical relevance per se." (PMID 38543187, 2024). "Some studies have found that the expression level of RELN in GBM is different from that of normal brain tissue or other types of brain tumors, which may be related to tumor invasiveness, growth rate, and treatment response." (PMID 40171042, 2025). "We initially hypothesized that, if reelin plays a contributing role in brain tumor biology, one would expect differing expression of this protein in healthy and malignant tissue." (PMID 38543187, 2024). "However, the involvement of reelin signaling in brain tumors has been poorly investigated." (PMID 34205192, 2021).
Cirrhosis (3 papers, 2017 to 2023). A chronic disorder of the liver in which liver tissue becomes scarred and is partially replaced by regenerative nodules and fibrotic tissue resulting in loss of liver function. "Similar results were observed in another study where reelin upregulation was present in liver cirrhosis as well as its alteration in glycosylation in plasma from cirrhosis patients." (PMID 34639052, 2021). "Reelin plasma levels (with alteration of reelin glicosylation) are increased both in experimental cirrhosis in mice and human cirrhotic patients." (PMID 28255385, 2017).
colitis (3 papers, 2022 to 2025). Inflammation of the colon. "Thus, its mRNA levels are much higher in sporadic than in colitis-associated adenocarcinoma, exhibiting, however, similar decreases in reelin mRNA abundance." (PMID 36290310, 2022). "Reelin, an extracellular matrix protein, is known to reduce the susceptibility to dextran sulfate sodium (DSS)-colitis." (PMID 39859530, 2025). "The results obtained in mice were similar to those in humans: reelin mRNA expression significantly increases in colitis and in colon precancerous lesions (ACF and polyps), and it decreases in adenocarcinomas induced by either AOM or AOM-DSS treatments." (PMID 36290310, 2022). "We previously reported that reelin absence increases colitis severity and colon tumorigenesis in mice and that reelin was upregulated in the colon of a mouse model of acute colitis and downregulated in human colon adenocarcinoma." (PMID 36290310, 2022). "Thus, in both mouse and human colons, reelin mRNA abundance increases in colitis and precancerous lesions and, thereafter, decreases as the injury severity increases throughout the cancer progression." (PMID 36290310, 2022).
COVID-19 (3 papers, 2023 to 2024). A disease caused by infection with severe acute respiratory syndrome coronavirus 2. "We observed increased Reelin expression in COVID-19 patients and accordingly, we sought to explore a causal link between this circulating protein and disease severity." (PMID 37441066, 2023). "Finally, to establish causality we have tested Reelin inhibition with the anti-Reelin antibody CR-50 in a COVID-19 mouse model." (PMID 37441066, 2023). "Taken together, these results demonstrate a direct pro-inflammatory function for Reelin in COVID-19 and identify this circulating protein as a potential biomarker and a drug target." (PMID 37441066, 2023). "This work was designed as a proof-of-concept study to test the relevance of Reelin as a biomarker and biotarget in COVID-19-related pathologies." (PMID 37441066, 2023). "Taken together, these results suggest that the anti-Reelin strategy is relevant in humans and effective in preventing the progression from mild to severe COVID-19, which is characterized by a transition to a hyperinflammatory state." (PMID 37441066, 2023). "In conclusion, this report shows that Reelin expression in plasma is increased during COVID-19 and correlates with disease activity." (PMID 37441066, 2023). "Reelin level was highly correlated with IL-1α, IL-4, IP-10, MIP-1β, and ICAM-1, suggesting a specific role for Reelin in COVID-19 progression." (PMID 37441066, 2023). "Reelin promotes vascular adhesion, permeability, and coagulation, which are all clinical hallmarks of severe COVID-19." (PMID 37441066, 2023). "For this purpose, we first measured Reelin expression in two COVID-19 rodent models, hamsters and hACE2 transgenic mice that were infected with SARS-CoV-2." (PMID 37441066, 2023). "On average, Reelin levels rise two to threefold under chronic or low-grade inflammatory conditions, and up to fivefold during acute or severe inflammation, as observed in COVID-19 patients experiencing a cytokine storm." (PMID 38607022, 2024). "In this study, we hypothesized that Reelin promotes endothelial dysfunction and participates in the propagation of hyperinflammation during COVID-19." (PMID 37441066, 2023). "We showed that Reelin was increased in COVID-19 patients and correlated with the disease activity." (PMID 37441066, 2023). "Thus, it demonstrates a direct role for Reelin in the progression to severe COVID-19, potentially through the promotion of endothelial dysfunction and coagulation." (PMID 37441066, 2023). "To confirm this observation in COVID-19 patients, we tested Reelin concentration in serum from healthy subjects, COVID-19 patients with a mild form (hospitalization with no ventilation), and COVID-19 patients with a severe form (hospitalization with ventilation)." (PMID 37441066, 2023). "Thus, we hypothesized that Reelin participates in endothelial dysfunction and hyperinflammation during COVID-19." (PMID 37441066, 2023). "Reelin level was correlated with IL-1α, IL-4, IP-10, MIP-1β, and ICAM-1, suggesting a specific role for Reelin in COVID-19 progression." (PMID 37441066, 2023).
Hypertension (3 papers, 2017 to 2025). The presence of chronic increased pressure in the systemic arterial system. "In the present study, our data revealed that Ang II-infused rats developed hypertension, proteinuria, and podocyte injury accompanied by Dab1 phosphorylation and increased reelin expression in kidney." (PMID 28676854, 2017). "Interestingly, a previous study has shown that DAB1 phosphorylation and increased reelin expression in the glomeruli are accompanied by hypertension, proteinuria, and podocyte injury in the Ang II-infused rats." (PMID 33924028, 2021).
liver cirrhosis (3 papers, 2021 to 2023). "Specifically, Reelin have been found to be up‐regulated in patients with liver cirrhosis in the liver and plasma." (PMID 37246473, 2023). "Even though it is not enough known about reelin signaling in the liver, it had been demonstrated that blood reelin levels are significantly increased in patients with liver cirrhosis and fibrosis, and even more elevated in HCC patients." (PMID 34639052, 2021).
lung adenocarcinoma (3 papers, 2016 to 2018). A carcinoma that arises from the lung and is characterized by the presence of malignant glandular epithelial cells. "The hazard ratio between high and low RELN expression was 0.64 for all lung adenocarcinoma, and 0.31 for stage I disease." (PMID 27071537, 2016). "We selected data from lung adenocarcinoma patients (n=720) and split samples between high and low expression of RELN by median, and explored whether high expression of RELN conferred an overall survival advantage." (PMID 27071537, 2016).
myocardial infarction (3 papers, 2021 to 2024). Gross necrosis of the myocardium, as a result of interruption of the blood supply to the area, as in coronary thrombosis. "Reelin is a secreted protein highly expressed in neurons and lymphatic capillaries, and lymphatic-derived reelin contributes to heart regeneration after myocardial infarction." (PMID 38051275, 2024). "The extracellular protein reelin (RELN) is recently identified as a lympho-endothelial secreted factor that enhances cardiac regeneration in neonatal mice and improves heart function after myocardial infarction." (PMID 33821373, 2021).
polymicrogyria (3 papers, 2019 to 2024). A developmental brain abnormality characterized by an excessive amount of small convolutions on the surface of the brain and cognitive dysfunction. "Our findings also revealed that all tested polymicrogyria-associated variants maintained overall secreted RELN levels but presented an enhanced capacity to induce neuronal aggregation, suggesting their potential contribution to the pathology." (PMID 38980724, 2024). "However, in the case of polymicrogyria-associated variants, the canonical RELN signaling cascade involving ApoER2/VLDLR appears to be unaffected based on the well-organized rosettes formed." (PMID 38980724, 2024). "Since whole-genome sequencing has yet to be performed for all polymicrogyria patients, the contribution of a deep intronic or regulatory variant in trans of the RELN variant or in another gene cannot be formally ruled out." (PMID 38980724, 2024). "Finally, RELN secretion and thus overall WT-RELN and mutant RELN levels are not perturbed or mildly impaired (for the R913C variant) in polymicrogyria patients, suggesting that protein levels are not contributing to the pathology." (PMID 38980724, 2024).
rheumatoid arthritis (3 papers, 2022 to 2025). A chronic, systemic autoimmune disorder characterized by inflammation in the synovial membranes and articular surfaces. "Reelin levels were also found to be increased in synovial fluid of patients with rheumatoid arthritis suggesting its role in musculoskeletal tissues." (PMID 35658052, 2022).
viral infection (3 papers, 2022 to 2025). "The possible cause of reduced expression of RELN in otosclerotic stapes could be due to a viral infection in different parts of mice brain." (PMID 35658052, 2022). "Mice treated with analogues of bacterial or viral infections at different gestational periods showed different neurodevelopmental profiles of hippocampal reelin and GAD67 cell number expression in the hippocampal dorsal or ventral stratum oriens of offspring." (PMID 36397016, 2022).
acute lymphoblastic leukemia (2 papers, 2013 to 2015). Leukemia with an acute onset, characterized by the presence of lymphoblasts in the bone marrow and the peripheral blood. "The one variant common in all gene enrichment analyses was RELN, which has been shown to be recurrently mutated in acute lymphocytic leukemia." (PMID 23349640, 2013). "Importantly, RELN is significantly mutated in human HNSCC, non-small cell lung cancer of smokers, and acute lymphoblastic leukemia." (PMID 26030765, 2015).
adenoma (2 papers, 2016 to 2022). A neoplasm arising from the epithelium. "Altogether, the results described so far indicate that in both, humans and mice, mRNA reelin expression changes from upregulation under inflammatory conditions and precancerous lesions to repression in adenoma and adenocarcinomas." (PMID 36290310, 2022). "In both, humans and mice, reelin mRNA abundance increased significantly in ulcerative colitis and slightly in polyps and decreased in adenomas and adenocarcinomas." (PMID 36290310, 2022). "Truncating mutations were also validated in SCUBE2, RELN, FBXW7, MLL3, WTX/FAM123B, OTUD7B and KPRP across the MAP and FAP adenomas." (PMID 26414517, 2016). "Reelin expression reduction coincides with the shift from non-adenomatous polyps to adenoma in humans, and from polyps to adenocarcinomas in mice." (PMID 36290310, 2022). "That is, reelin mRNA abundance decreases as disease severity progresses from ulcerative colitis to adenocarcinoma, and the shift from reelin upregulation to repression occurs in the progression from non-adenomatous polyps to adenoma." (PMID 36290310, 2022).
autoimmune disease (2 papers, 2023 to 2024). A disorder resulting from loss of function or tissue destruction of an organ or multiple organs, arising from humoral or cellular immune responses of the individual to their own tissue constituents. "However, it is important to keep in mind that Reelin has a variety of peripheral effects and that increased peripheral levels of Reelin might affect the function of some organs and promote autoimmune diseases." (PMID 37891846, 2023).
Cerebellar atrophy (2 papers, 2017 to 2020). Cerebellar atrophy is defined as a cerebellum with initially normal structures, in a posterior fossa with normal size, which displays enlarged fissures (interfolial spaces) in comparison to the foliae secondary to loss of tissue. "The phenotype of homozygous Reln‐del mice was similar to that of reeler mice with cerebellar atrophy, dysplasia of the cerebral layers, and abrogated protein levels of cerebral reelin." (PMID 32065683, 2020).
cerebral infarct (2 papers, 2021 to 2025). "Corresponding in vivo experiments have illustrated that pre-administration of exogenous Reelin protein into the ventricles prior to middle cerebral artery occlusion reduces cerebral infarct volume and promotes neuronal survival." (PMID 40442071, 2025). "Similarly, after postnatal cerebral infarction in rodents, no protective role of reelin was observed during recovery." (PMID 34199942, 2021).